IDH1 (isocitrate dehydrogenase (NADP(+)) 1)
Diseases named in the same sentence as IDH1 in open-access papers (continued):
Sharing a sentence is not in itself a finding about the gene and the disease.
glioma (continued). "A specific inhibitor of mutant IDH1 R132H, AGI-5198 impairs the production of D-2-HG, inhibits cell proliferation and enhances the differentiation of glioma." (PMID 30305430, 2018). "Our in vitro studies were conducted using high grade glioma GBM30 neurospheres (primary) and U87 MG established cell lines since we found that GBMs (which are nearly all IDH1/2 WT) have significantly higher TAGLN2 levels than LGGs." (PMID 30647847, 2018). "TAGLN2 mRNA levels were significantly different between IDH1/2 WT grade II (n=21), grade III (n=52) and grade IV (n=133) gliomas from the TCGA database (p< 0.0001)." (PMID 30647847, 2018). "We validated these findings in an additional institutional cohort of IDH1/2 WT (n=7) versus IDH1/2 mutant (n=23) grade II and III gliomas." (PMID 30647847, 2018). "Given recent findings that high tumor 2-HG levels have been shown to block cellular differentiation in a variety of IDH1 mutant tumor types, we next examined the ability for MRK-A to alter glioma stem cell marker expression in BT14212–15,17." (PMID 29062039, 2017). "Interestingly, albeit no formerly known association with tumor, NPIPB15 I419T point mutation was unanimously detected in three cases, suggesting its variation could be a common event in Chordoma progression such as IDH1 in glioma and acute myeloid leukemia (AML)." (PMID 27901492, 2017). "Clinical trials are also underway to target mutant IDH1 and IDH2 in AML, gliomas, myelodysplastic syndrome, and other solid tumors." (PMID 28653623, 2017). "Given MiSL's prediction in AML and glioma and the positive validation of the IDH1mut-ACACA SL relationship in AML, it seems plausible that IDH1mut-ACACA SL relationship is valid in other IDH1 mutant tumours." (PMID 28561042, 2017). "To investigate which genes are differentially expressed in IDH1 wild type (IDH1WT) and IDH1R132H glioma cells, we performed microarray analysis." (PMID 28445981, 2017). "Context dependency of TET (dys)function in cancer is further indicated by lack of correlation between 5-hmC levels and IDH1/2 mutations in slow growing infiltrative gliomas, although these mutations drive overproduction of the 2-HG metabolite that may interfere with α-KG actions as a co-factor." (PMID 28032215, 2017). "The objective of this study was to provide insight into the differences between IDH1 and IDH2 mutant gliomas." (PMID 27245697, 2016). "To investigate the different clinical and molecular characterization between IDH1 mutant and IDH2 mutant gliomas, we studied a cohort of 811 patients consisting 448 IDH1 mutant, 18 IDH2 mutant and 345 IDH1/2 wild-type gliomas." (PMID 27245697, 2016). "Hundreds of lncRNAs were specifically expressed in each of the three lower grade glioma (LGG) subtypes (IDH1/2 wt, IDH1/2 mut, and IDH1/2 mut 1p19q codeletion) and the four subtypes of GBMs (classical, mesenchymal, neural, and proneural)." (PMID 27923049, 2016). "The most common mutations affect the genes coding isocitrate dehydrogenases: IDH1 (cytosolic) and IDH2 (mitochondrial) and are detected in about 70–80% of grade II/III gliomas (and secondary glioblastomas, grade IV)." (PMID 27145078, 2016).
glioma (continued). "To experimentally test the role of TNC in ECM stiffness and glioma aggression, we knocked down TNC in primary GBM cells (WT IDH1) and assessed the resulting effects on ECM stiffness and tumour aggression." (PMID 27820599, 2016). "With regard to targeting neoantigens in lower-grade glioma, mutant isocitrate dehydrogenase type 1 (IDH1) is carried by more than 70% of diffuse grade II and III gliomas, and targeting IDH1 by peptide vaccination has shown efficacy." (PMID 27057463, 2016). "There is mounting evidence that a subset of IDH1 wild-type WHO grade II and III astrocytic and mixed gliomas have similar gene expression profiles to GBs, and have inferior survival outcomes compared to other tumors of similar WHO grade and histology." (PMID 26646075, 2015). "We also found that patients with IDH1/2 mut gliomas and high Ki-67 expression (Group 2) had worse clinical outcome than did patients with DH1/2 wt gliomas and low Ki-67 expression (Group 3)." (PMID 26338964, 2015). "Recent study has demonstrated a link between IDH1 function and BCAT1 expression in gliomas, as BCAT1 was shown to be involved in tumor growth and disease progression only in gliomas with wild-type (non-mutated) IDH1." (PMID 26372729, 2015). "In this study, detection of mutant IDH1 in LGG patients depended on tumor volume and in high-grade glioma patients on the presence of contrast enhancement as visualized by MR imaging." (PMID 25720744, 2015). "This metabolite, 2-hydroxyglutaric acid, or 2-HG, has generated a tremendous amount of interest recently because it is also produced in large quantities by the mutant forms of IDH1 and IDH2 that occur in gliomas, acute myeloid leukaemias and other cancers." (PMID 24581008, 2014). "In summary, our study is the first study in investigating the IDH1/IDH2 status in paired primary and recurrent gliomas in Chinese patients." (PMID 23840696, 2013). "In conjunction with increased differentiation in IDH1 R132H glioma cells, DAC also exerts its antitumor effects by reducing the tumorigenic potential of IDH1-mutant cells by decreasing colony formation in vitro and xenograft growth in vivo." (PMID 24077826, 2013). "However prognosis of patients with IDH1 mutated glioma is not confined to those receiving chemotherapy, suggesting that other factors may also be important." (PMID 24252742, 2013). "Mutations in the enzyme cytosolic isocitrate dehydrogenase 1 (IDH1) are found in more than 68% of WHO grade II and III gliomas and secondary glioblastomas (GBM) in human brain cancers." (PMID 24324372, 2013). "First, we examined 24 malignant gliomas which showed strong immunoreactivity for mutant IDH1, including 9 GBM, 13 anaplastic astrocytomas, and 2 anaplastic oligodendrogliomas identified on two glioma tissue microarrays generated at Johns Hopkins Hospital." (PMID 22298889, 2012). "Strikingly, the mutations are single amino acid substitutions at an arginine residue in the active site of the enzyme (e.g., R132 for IDH1 and R172 in IDH2 in gliomas or R140 for IDH2 in AML)." (PMID 23162793, 2012). "This analysis allowed us to define two highly recurrent genetic signatures in gliomas: IDH1/ATRX (I-A) and IDH1/CIC/FUBP1 (I-CF)." (PMID 22869205, 2012).
glioma (continued). "Mutations in metabolic enzymes, in particular isocitrate dehydrogenase enzymes (IDH1 and IDH2), have been shown to be involved in glioma development and would facilitate HIF-1 protein stabilization." (PMID 20735813, 2010). "The NCT02454634 trial detected immune responses in IDH1 R132H+ gliomas but no survival benefit with adjuvant therapy." (PMID 40443668, 2025). "Based on these preclinical findings, researchers conducted a multicenter phase I clinical trial to evaluated the safety, feasibility, and immunotherapeutic efficacy of mutant IDH1-targeted vaccination in newly diagnosed WHO grade III and grade IV glioma patients." (PMID 40661781, 2025). "While there is overwhelming evidence that D-2HG acts as an oncometabolite in cells that express mutant IDH1/IDH2, there is limited evidence indicating that changes in D2hgdh expression or activity drive glioma progression, with only a handful of studies hinting this possibility." (PMID 40236175, 2025). "IDH1/2 mutants consume NADPH to produce D-2-HG, which similarly inhibits α-KG–dependent chromatin and DNA demethylases, driving a hypermethylation phenotype that can initiate tumorigenesis, particularly in gliomas and hematologic malignancies." (PMID 41551149, 2025). "The PN-L subclass includes IDH1-mutant gliomas, which are no longer classified as GBM under the 2021 WHO framework." (PMID 40234567, 2025). "This suggests that while KNN is exceptionally powerful in identifying IDH1-positive cases, its ability to accurately classify IDH1-negative gliomas requires further optimization." (PMID 40299088, 2025). "LSM2 expression was significantly elevated in gliomas, particularly in GBM and in tumours with 1p/19q non-deletion or IDH1 mutation (p < 0.001)." (PMID 40365337, 2025). "Notably, in IDH1/2-mutant glioma, CDKN2A/B deletion and EGFR amplifications were rare but confined to high-grade gliomas." (PMID 41377022, 2025). "IDH1 mutation status is an important molecular marker that has been used by the World Health Organization Classification of Tumors of the Central Nervous System to define GBM as IDH1-wildtype, and IDH-mutant gliomas are characterized as astrocytoma or oligodendroglioma." (PMID 40507361, 2025). "Compared to the normal brain tissue, a distribution of this probe into gliomas was evident regardless of IDH1 genotype." (PMID 40171868, 2025). "It recruited 52 adult patients with recurrent or refractory grade 2–4 IDH1- or IDH2-mutant glioma (22 non-enhancing and 30 enhancing), from 2015 to 2017." (PMID 40867259, 2025). "Reviews of glioma immunotherapy identify both peptide vaccines (e.g., rindopepimut, IMA950, IDH1) and CAR-T cells as promising combination options that may overcome antigen escape and limited immune persistence." (PMID 41441679, 2025). "Notably, higher levels of CD68-, CD163-, and CD206-positive glioma-associated microglia and macrophages correlate with prolonged survival in IDH1 R132H-non-mutant glioblastoma patients, suggesting that modulation of these immune populations could have therapeutic benefits." (PMID 40076738, 2025). "Given these challenges, vorasidenib—a selective inhibitor of mutant IDH1 and IDH2—may represent a promising and potentially transformative adjunct in the surgical management of low-grade gliomas." (PMID 41008917, 2025). "Gliomas with IDH mutations, particularly in IDH1 and IDH2, exhibit longer overall survival (OS) compared to gliomas lacking these mutations, also referred to as IDH-wt." (PMID 41541926, 2025). "Regardless of IDH1 genotype, glioma tissues exhibited much higher levels of GSH compared to adjacent non‐malignant tissues." (PMID 40171868, 2025).
glioma (continued). "We selected six of these inhibitors for further investigation, evaluating their effects both alone and in combination with TMZ in commercially available U87 MG wild-type and IDH1 mutant (IDH1 WT and MUT) glioma cells and patient-derived cells established from glioma organoids (GBO-PDC)." (PMID 41285884, 2025). "Among the 48 gliomas, 22 (45.8%) were IDH1-positive and 26 (54.2%) were IDH1-negative, with no statistical difference in age between the two groups and a statistical difference in histological grading (p < 0.05)." (PMID 40944023, 2025). "Their study retrospectively evaluated treatment-naïve patients with IDH1-mutant, non-enhancing, radiologically active grade 2/3 gliomas who subsequently received ivosidenib." (PMID 40136387, 2025). "In several IDH1-mutant cancers, including intrahepatic cholangiocarcinoma (ICC), glioma, melanoma, chondrosarcoma, and prostate cancer, this includes the epigenetic repression of cGAS, a DNA sensor critical for activating the STING pathway and type I interferon signalling." (PMID 40931345, 2025). "DLL3 has also been reported on; it was found that high levels of the DLL3 protein is prognostic in IDH1 mutant gliomas but not in GBM, which tracks well in our results." (PMID 39941811, 2025). "In a comparative study by James P. Solomon’s Department of Pathology and Laboratory Medicine (Weill Cornell Medicine, New York), 39 samples from glioma patients treated on the New York-Presbyterian Hospital (NYPH) campus between 2018 and 2023 were examined regarding IDH1/2 status." (PMID 40075667, 2025). "Furthermore, immunohistochemistry staining with the IDH1 mutant enzyme antibody IDH1‐R132H indicated that Au‐R12P effectively differentiates between IDH1‐WT and IDH1‐MUT gliomas allografts." (PMID 40171868, 2025). "In contrast, IDH1/2 mutations are absent in IDH-wt GBMs (defining the subtype), but in rare IDH-mutant astrocytoma grade 4 (~10% of grade 4 gliomas), they confer greater radiosensitivity and better prognosis (ESCAT I)." (PMID 41007699, 2025). "The DWI, DCE and APTW images of 309 patients with glioma confirmed by pathology were retrospectively analyzed and divided into the IDH-1 group (IDH-1(+) group and IDH-1(-) group) and Ki-67 group (low expression group (Ki-67 ≤ 10%) and high expression group (Ki-67 > 10%))." (PMID 39285364, 2024). "Both VPA and a selective FASN inhibitor TVB-2640 rewired the lipidome and promoted apoptosis in an IDH1 MT but not in an IDH1 WT glioma cell line." (PMID 39149696, 2024). "NEC gliomas are IDH1 non-mutant gliomas that express ATRX, lack necrosis or microvascular proliferation, and do not have chromosome 7 gain, chromosome 10 loss, EGFR amplification, or TERT promoter mutation." (PMID 39135755, 2024). "Our data suggested that inhibition of HMGCR also inhibited the growth of IDH1 MT glioma cell lines, so it is possible that inhibition of both de novo lipogenesis and cholesterol metabolism contribute to the growth inhibitory effect by VPA." (PMID 39149696, 2024). "In summary, our results demonstrate that regardless of their etiology (due to lifetime RFR exposure or arising spontaneously), rat gliomas are primarily Idh1/2 wild type unlike most human gliomas." (PMID 38232086, 2024). "The IDH1 transfection experiments also suggest that glioma cellular growth is downregulated by the lack of 2-oxoglutarate rather than accumulation of oncometabolite 2-hydroxyglutarate." (PMID 38673928, 2024). "Then we investigated whether a synergistic anti-glioma effect existed between D-2HG and TMZ to elucidate the mechanisms behind the improved efficacy of TMZ in IDH1-mutant glioma patients." (PMID 38982076, 2024).
glioma (continued). "This analysis aimed to elucidate the molecular interactions of mucins with IDH1 and MGMT via EGFR, providing insights into their potential roles in glioma-related pathways and broader biological processes, and the resulting PPI enrichment p-value was <1.0 × 10−16, ranging from 0.99 to 0.42." (PMID 39767713, 2024). "ITGA1 was obviously higher in grade 3 than in grade 2 glioma, and it was upregulated significantly in IDH1 wild-type and 1p19q non-codeficient LGG as compared to IDH mutant and 1p19q codeficient LGG." (PMID 39502752, 2024). "Glioblastoma is a glial tumor that is IDH1 non-mutant with necrosis and/or microvascular proliferation or with chromosome 7 gain and chromosome 10 loss or EGFR amplification or TERT promoter mutation." (PMID 39135755, 2024). "Additionally, vorasidenib, an IDH1/IDH2 inhibitor, has shown efficacy in extending progression-free survival in patients with IDH-mutant gliomas, providing an opportunity to delay treatments like radiation and chemotherapy, thus preserving cognitive function." (PMID 39439623, 2024). "Inhibitors that directly target MT IDH1 and block 2-HG have efficacy in low-grade IDH1 mutant gliomas but have not been proven to be beneficial for mutant high-grade gliomas." (PMID 39149696, 2024). "Apart from U87, there is no other established glioma cell line as an isogenic pair differing just in the IDH1 status." (PMID 38711090, 2024). "Although VPA decreased chromatin accessibility in both WT and MT cell lines, the loss of promoter chromatin accessibility for lipogenic genes was significant in IDH1 MT but not IDH1 WT glioma cell lines." (PMID 39149696, 2024). "On the other hand, in the 75 Grade 4 glioma cases, 14 cases (18.6%) had wildtype IDH1 and 74 cases (98.6%) had no EGFR-amp." (PMID 38893240, 2024). "Additionally, other hotspots have also been studied in specific cancers, such as IDH1 and IDH2 in gliomas, EGFR in the lung, and BRAF in skin cancer." (PMID 38473427, 2024). "The results of the spheroid model showed that the genes TRPC3, TRPC4, TRPC5, and TRPV1 were upregulated in glioma cells either wild‐type isocitrate dehydrogenase 1 (IDH1) or the IDH1 R132H mutant, with or without NaCl treatment." (PMID 39189437, 2024). "However, additional studies are required to explore the combined impact of IDH1 genotype and LINC00475 expression on glioma prognosis." (PMID 38405130, 2024). "IDH1 is an important biomarker in gliomas, whereas PCDHGA10 mutation has not been reported to correlate with gliomas." (PMID 39208202, 2024). "The second is a mutation in the IDH genes, IDH1 or IDH2, which is not specific to particular histopathological glioma subtypes but is linked with cellular metabolism." (PMID 38019450, 2024). "Several clinical trials investigating IDH-1 inhibitors among patients with gliomas are underway; however, their efficacy is not always approved." (PMID 38633919, 2024). "And it is noteworthy that even without TMZ treatment, patients with IDH1-mutant gliomas exhibit better therapeutic efficacy compared to those with wild-type tumors who receive TMZ." (PMID 38982076, 2024). "Mutant IDH1 and IDH2 undergo a conformational change resulting in enzymatic activity which converts α-ketoglutarate to its structural derivative 2-hydroxyglutarate which has been found at high concentrations in mutant gliomas." (PMID 38525424, 2024). "Among the 26 grade 3 glioma samples, 4 cases (15.3%) had wildtype IDH1, and 26 cases (100%) had no EGFR-amp." (PMID 38893240, 2024). "Conversely, the study did not detect mutations in the IDH1/2 and BRAF genes in the transformed tumors, which are typically found in other gliomas." (PMID 39457636, 2024). "Our lipidomic study suggested that although VPA targets FASN in IDH1 MT glioma cell lines, it does not deplete palmitate." (PMID 39149696, 2024). "Ivosidenib, a selective mIDH1 inhibitor, was tested in a phase I trial that enrolled IDH1-mutant glioma patients who had recurred or not responded to standard-of-care therapy." (PMID 39025958, 2024).